INS (insulin)
Diseases named in the same sentence as INS in open-access papers (continued):
Sharing a sentence is not in itself a finding about the gene and the disease.
autoimmune disease (continued). "T1DM is an autoimmune disease which is characterized by the destruction of insulin-producing beta cells in the pancreas and a complete deficiency in insulin secretion." (PMID 35164321, 2022). "Type 1 diabetes (T1D) is an autoimmune disease caused by the destruction of the insulin‐producing β‐cells within the pancreatic islets of Langerhans." (PMID 35191175, 2022). "Emotional eating was unrelated to the type of insulin therapy (with pump or multiple daily injections) and to associations with other autoimmune diseases." (PMID 36528643, 2022). "Type-1-diabetes (T1D) is an autoimmune disorder caused by the inability of the pancreas to produce sufficient insulin, leading to high blood glucose levels." (PMID 36359215, 2022). "Type 1 diabetes (T1D) is an autoimmune disease caused by the destruction of the insulin‐producing β‐cells within the pancreas." (PMID 35191175, 2022). "T1DM is a chronic, genetically determined, autoimmune disease caused by the patient’s inability to secrete insulin as a result of autoimmune destruction of pancreatic β cells." (PMID 35745227, 2022). "This is indicative of the fact that this autoimmune disease causes a complete failure of the β cells to secrete insulin and thus maintain glucose homeostasis, necessitating the use of exogenous insulin replacement therapy." (PMID 34940547, 2021). "Type 1 DM is principally occurring because of the obliteration of the insulin-producing pancreatic beta cells in the Langerhans islets because of an autoimmune disease that causes a flat-out insufficiency of insulin." (PMID 34497854, 2021). "T1D is a complex T cell-mediated autoimmune disease, resulting in destruction of the insulin-producing β cells and a deficiency in insulin secretion." (PMID 35156097, 2021). "The disease is an autoimmune disorder that is caused by infiltration of inflammatory cells in islets of Langerhans, consequently destructing the insulin-producing β-cells." (PMID 33628471, 2021). "T1D is an autoimmune disease in which the loss of tolerance to self-antigens including insulin, GAD65, IA-2, and ZnT8 leads to autoreactive T cell responses that promote the destruction of pancreatic β cells." (PMID 33671312, 2021). "Lastly, the TNFRSF13C (BAFF) gene regulates insulin sensitivity and is associated with autoimmune diseases." (PMID 33472578, 2021). "Type 1 diabetes (T1D) is an autoimmune disease caused by immune destruction of the insulin-producing β cells within the pancreatic islets of Langerhans, leading to a lifelong dependence on daily administrations of insulin." (PMID 33095259, 2021). "Autoimmune disease necessarily involves destruction of autoantigen-associated tissue and in the case of T1D, insulin-producing β cells are targeted first with the eventual destruction of the entire islet of Langerhans." (PMID 34433860, 2021). "Type B insulin resistance (TBIR) is an autoimmune disease caused by the presence of immunoglobulin G (IgG) polyclonal antibodies, which competitively inhibit the binding of insulin to the insulin receptor." (PMID 32337291, 2020). "Type 1 diabetes is an autoimmune disease characterized by immunological pancreatic attack by autoreactive T cells and auto-antibodies with severe loss of insulin secretion." (PMID 30346951, 2018). "IAS is frequently associated with other autoimmune diseases (mainly Graves’ Disease), rheumatologic diseases, previous exposure to exogenous insulin, and use of medications." (PMID 30462811, 2018). "T1D is a T-cell mediated glandular autoimmune disease that develops in genetically susceptible individuals and results in destruction of the insulin-producing β cells." (PMID 29941778, 2018). "T1D is an autoimmune disease caused by the selective disruption of pancreatic islet cells by autoreactive T lymphocytes and to lifelong dependence on exogenous insulin therapy." (PMID 28491063, 2017).
autoimmune disease (continued). "T1D is an autoimmune disease, whereby genetics contribute to the immunoprofiles responsible for the destruction of β-cells and loss of insulin production." (PMID 28119693, 2016). "It has been shown that the second susceptibility locus for autoimmune disease, after HLA, corresponds to a mini satellite in the insulin gene (INS-VNTR) and in Caucasians populations this VNTR is in linkage disequilibrium with −23 HphI SNP." (PMID 26273670, 2015). "Type-1 diabetes (T1D) is an autoimmune disease caused by T-cell-induced destruction of the insulin-producing β-cells of the pancreas." (PMID 25339185, 2014). "One of the genes in anorexia, namely AKAP6, is also associated to fasting insulin-related traits as well as the autoimmune disease Ankylosing spondylitis." (PMID 23936387, 2013). "Positive islet autoantibodies in autoimmune diabetes patients are thought to indicate a progressive autoimmune disease in the beta cells associated with a gradual decrease in insulin secretion." (PMID 23452723, 2013). "Inflammation associated with the T-cell-mediated autoimmune disease T1D results in the loss of the insulin-producing β cells in the pancreatic islets of Langerhans." (PMID 22838494, 2012). "T1D is a spontaneous autoimmune disease associated with the pancreas in which damage to the insulin-producing β-cells disturbs glucose metabolism and leads to a series of complications." (PMID 21765853, 2011). "In addition, it causes reduced insulin secretion, insulin resistance, breakdown of proteins in various tissues (skeletal muscles, bones), muscle atrophy, osteoporosis, autoimmune diseases, carcinogenesis, and psychiatric disorders." (PMID 39857890, 2025). "The cause of the disease is either lower insulin production due to genetic mutation or hereditary, modification in habitual eating patterns, or insulin resistance caused by over secretion of insulin or chronic inflammations leading to autoimmune disorders." (PMID 35566252, 2022). "It is an autoimmune disease characterized by the loss of insulin-producing β cells of the pancreas, leading to an inability to use glucose as fuel, thus requiring life-saving exogenous insulin administration." (PMID 34081017, 2021). "Therefore, it is recommended that clinicians should be alert to the positive insulin antibody, especially the risk of other autoimmune diseases in patients with positive multi-insulin antibodies." (PMID 32481446, 2020). "T1D, an autoimmune disease resulting from immune-mediated destruction of the insulin-producing β-islet cells of the pancreas, causes substantial morbidity and mortality and requires life-long insulin treatment." (PMID 28510587, 2017). "Firstly, T1DM is classified as an autoimmune disease caused by the destruction of β-cells that are responsible for the production of insulin, resulting in the long-term administration of insulin through daily injections, insulin pump therapy and automated insulin delivery systems." (PMID 38791917, 2024). "Organ-specific autoimmune diseases involve a target-specific destruction leading to excess, or, more often, a deficiency of the cell-specific function of the target organ; in T1D, that process involves the destruction of the insulin-secreting cells of varying severity." (PMID 28829396, 2017). "Type 1 diabetes (T1D) is an autoimmune disease, resulting in diminished islet integrity and destruction of the insulin‐secreting beta cells." (PMID 38798081, 2025). "In contrast, in other fields—especially in insulin therapy and in the case of certain drugs used for autoimmune diseases (adalimumab and etanercept)—the transition to biosimilars, although steadily growing, remains incomplete." (PMID 40283918, 2025). "Since T1DM is an autoimmune disease leading to absolute endogenous deficiency, T1DM patients must carefully monitor their BG levels and precisely adjust their insulin dosages to maintain glycemic homeostasis." (PMID 40136987, 2025).
autoimmune disease (continued). "This study aimed to compare the efficacy and safety of OADMs and sliding scale insulin (SSI) in patients with autoimmune diseases who developed GCIH." (PMID 41464548, 2025). "Type 1 diabetes (T1D) is an autoimmune disease characterized by the destruction of insulin-producing β-cells in the pancreatic islets." (PMID 40977709, 2025). "Type 1 diabetes (T1D) is an organ-specific multifactorial autoimmune disease that progressively leads to complete destruction of the insulin-producing pancreatic islet β-cells and the need for lifelong insulin therapy." (PMID 40014914, 2025). "The present study included patients with a wide spectrum of autoimmune diseases, which makes it difficult to generally discuss the mechanisms of action of OADMs or insulin regimens on GCIH." (PMID 41464548, 2025). "Type 1 diabetes (T1D) is an autoimmune disease that leads to the destruction of insulin-producing pancreatic cells, necessitating exogenous insulin administration." (PMID 39702741, 2025). "Type 1 diabetes (T1D) is an autoimmune disease characterized by destruction of insulin-producing β-cells in the pancreatic islets by autoantigen-specific T cells." (PMID 40977709, 2025). "T1DM is an autoimmune disease where T lymphocytes mistakenly attack insulin-producing β-cells in the pancreas." (PMID 41162165, 2025). "T1DM is an autoimmune disease characterized by the destruction of insulin-producing β-cell in the pancreas, driven by autoreactive T cells and an imbalance in immune tolerance mechanisms." (PMID 40370441, 2025). "T1DM is an autoimmune disease characterized by the targeted destruction of insulin-producing pancreatic islet β-cells." (PMID 40370441, 2025). "These investigative studies indicate that T1D is primarily an autoimmune disease, driven by autoreactive T cells that target insulin-producing pancreatic β-cells." (PMID 39451194, 2024). "T1D is a typical organ-specific autoimmune disease in which the predominant immune response is mediated by T cells targeting the islet insulin-producing beta cells." (PMID 38297222, 2024). "This proactive approach aims to prevent long-term sequelae, such as type 1 DM, an autoimmune disease that destroys insulin-producing pancreatic beta cells." (PMID 39234544, 2024). "T1D is an autoimmune disorder marked by the destruction of insulin-producing β cells in the pancreatic islets, resulting from a loss of immunological tolerance." (PMID 39460283, 2024). "The current clinical treatment for T1D, an autoimmune disease where β-cells are lost, is the artificial application of exogenous insulin, either through injections or insulin pumps." (PMID 39137218, 2024). "Type 1 Diabetes (T1D) is an autoimmune disease characterized by a state of absolute low insulin production that can quickly lead to life-threatening diabetic ketoacidosis if insulin needs are not met appropriately." (PMID 38190377, 2024). "Type 1 diabetes (T1D) is an organ-specific autoimmune disease involving the demise of the insulin-producing beta cells in the pancreatic islets of Langerhans, leading to insulin insufficiency." (PMID 39173948, 2024). "T1DM is an autoimmune disease characterized by the progressive destruction of insulin-secreting pancreatic β cells in pancreatic islets and is caused by a complex interaction between genetics and the environment." (PMID 38475833, 2024). "T1D is an autoimmune disease that begins when a human's own immune cells attack and destroy insulin‐producing beta cells in the pancreas, resulting in a lack of beta cells, a cessation of insulin production, and uncontrolled blood sugar levels." (PMID 39081515, 2024). "Type 1 diabetes (T1D) is an autoimmune disease characterized by the destruction of insulin-producing β cells." (PMID 38903498, 2024). "T1D is an autoimmune disease, which typically presents at a young age and requires insulin therapy from disease onset, whereas T2D usually develops later in life and can initially be managed with lifestyle modifications." (PMID 39338114, 2024).
autoimmune disease (continued). "Type 1 diabetes (T1D) is an autoimmune disease involving T cell-mediated destruction of the insulin-producing beta cells in the pancreatic islets of Langerhans." (PMID 39173948, 2024). "T1D is an autoimmune disease in which T cells continuously attack and destroy insulin-secreting β-cells in the islets of Langerhans, and it is mainly characterized by insulitis." (PMID 39767698, 2024). "Type 1 diabetes (T1D) is an autoimmune disease in which β cells are selectively destroyed, leading to chronic hyperglycemia and the need for exogenous insulin therapy." (PMID 39767698, 2024). "Type 1 diabetes (T1D) is an autoimmune disease that results from the destruction of the insulin-producing pancreatic beta cells, ultimately leading to dependence on insulin." (PMID 36839302, 2023). "Type 1 diabetes (T1D) is an organ-specific autoimmune disease characterized by immune-mediated destruction of insulin-secreting pancreatic beta cells, ultimately resulting in lifelong dependence on exogenous insulin." (PMID 37249465, 2023). "It was observed that patients suffering from both autoimmune diseases compared to those suffering only from T1DM have a lower need for basal insulin and an increased need for post-prandial insulin." (PMID 36983604, 2023). "Instead of protecting the body from foreign substances, the immune system attacks the other systems, tissues, or cells in the autoimmune disease, including insulin-producing pancreatic beta-cells." (PMID 37346355, 2023). "T1DM is an autoimmune disease typically occurring in childhood or early adulthood, resulting in the inability to produce enough insulin because of the destruction of insulin-producing islet cells in the pancreas." (PMID 36780227, 2023). "T1DM is an autoimmune disease in which T cells attack and destroy insulin-producing beta cells in the pancreatic islets." (PMID 38169604, 2023). "T1DM is an autoimmune disease characterized by the destruction of insulin-producing cells in the pancreas, resulting in insufficient production of insulin and, subsequently, higher glucose levels." (PMID 37046861, 2023). "Insulin shortage results from the autoimmune disease T1DM, caused by the death of the pancreatic beta cells producing insulin." (PMID 38022113, 2023). "It is primarily classified as an autoimmune disorder, where the pancreatic β-cells are unable to secrete sufficient insulin." (PMID 36359215, 2022). "These adipokines signal through major metabolic pathways such as insulin signaling, inflammation, food intake, and energy expenditure, and exert their functions in cardiovascular, reproductive, and autoimmune diseases." (PMID 35892989, 2022). "Insulin replacement therapy faces great challenges to this autoimmune disease, requiring highly frequent daily administration." (PMID 35964125, 2022). "Type 1 diabetes (T1D) is an autoimmune disease in which antibodies are produced against various elements of pancreatic β-cells; the islets producing insulin become deteriorated and, eventually, are completely destroyed, which causes a lack of insulin." (PMID 35008906, 2022). "Type 1 diabetes (T1D) is an autoimmune disease characterized by the T-cell-mediated destruction of insulin-producing β-cells in pancreatic islets." (PMID 35456512, 2022). "Type 1 diabetes (T1D) is an autoimmune disease that selectively destroys insulin-producing β-cells in the pancreas." (PMID 35864094, 2022). "T1DM is an autoimmune disease characterized by the T cell-mediated destruction of insulin-producing β cells in pancreatic islets." (PMID 36090587, 2022). "In this regard, it is believed that our design based on the STAMP innovated the approach of applying parasite-products to autoimmune disorders, and became an effective supplement to external insulin in the T1DM treatment." (PMID 35964125, 2022). "Type 1 diabetes (T1D) is a T cell–mediated autoimmune disease that affects the insulin-producing beta cells of the pancreatic islets." (PMID 34044020, 2021).
autoimmune disease (continued). "Type 1 diabetes (T1D) mellitus is a chronic, T lymphocyte-mediated autoimmune disease leading to destruction of pancreatic Langerhans β-cells, endogenous insulin secretion decline and consequent hyperglycemia." (PMID 32936764, 2021). "T1DM is an autoimmune disease driven by CD4+ T cells that destroy insulin-secreting beta cells in the pancreas." (PMID 33672515, 2021). "T1D is an autoimmune disease that results from immune attack on the pancreatic β cells responsible for producing insulin and is characterized by failure of the pancreas to produce sufficient levels of insulin." (PMID 34805251, 2021). "TIDM is an autoimmune disease driven by the activation of T lymphocytes against pancreatic ß-cells, which attacked the pancreatic ß-cells and decreased insulin production." (PMID 34444092, 2021). "T1D is an autoimmune disease, in which the immune system destroys insulin-producing β cells of the pancreas." (PMID 34564296, 2021). "It belongs to the autoimmune diseases and it is the vital insulin-secreting pancreatic β-cells that are destroyed." (PMID 33477763, 2021). "Type 1 diabetes (T1D) has been identified to be an autoimmune disease for which CTLs play an important role by destroying the insulin-producing pancreatic beta-cells." (PMID 34248978, 2021). "Type 1 diabetes (T1D) is an autoimmune disease characterized by autoreactive T cell-mediated destruction of insulin-producing pancreatic beta-cells." (PMID 34691077, 2021). "T1DM is an autoimmune disease; it occurs due to the destruction of insulin-producing pancreatic β cells, and the patients are entirely reliant on exogenous insulin injection." (PMID 34827690, 2021). "The first autoimmune disease to be interrogated for prediagnostic autoantibodies was T1D, in which autoantibodies against autoantigens such as insulin, GAD65, and IA2 are present approximately 4–10 years before patients require insulin replacement therapy." (PMID 33763057, 2021). "Type 1 diabetes (T1D) is widely considered to be a T cell driven autoimmune disease resulting in reduced insulin production due to dysfunction/destruction of pancreatic β cells." (PMID 33679717, 2021). "T1D is a highly heritable autoimmune disease that results from T cell-mediated destruction of insulin-producing pancreatic β cells." (PMID 33712626, 2021). "Type 1 diabetes (T1D) is an autoimmune disease characterized by T cell-mediated destruction of the insulin-producing β cells in the pancreatic islets of Langerhans1." (PMID 34433860, 2021). "T1D patients diagnosed with any other autoimmune disease and receiving any kind of drugs except insulin therapy were excluded from this study." (PMID 32936764, 2021). "Individuals who require insulin at doses greater than 3 U/kg/day and have concomitant autoimmune diseases should be investigated for TBIRS." (PMID 32813762, 2020). "Type 1 diabetes (T1D) is an autoimmune disease in which insulin-producing pancreatic β-cells are destroyed." (PMID 32321922, 2020). "Type 1 autoimmune diabetes is a classical organ-specific autoimmune disease resulting from immune-mediated destruction of pancreatic β-cells producing insulin." (PMID 33013834, 2020). "Type 1 diabetes (T1D) is a T cell-driven autoimmune disease targeting the insulin producing β cells in the pancreas." (PMID 33603744, 2020). "Type 1 autoimmune diabetes is an autoimmune disease characterized by specific destruction of pancreatic β-cells producing insulin." (PMID 33013834, 2020). "Type 1 diabetes (T1D) is a polygenic autoimmune disease characterized by immune-mediated destruction of insulin-producing β-cells." (PMID 32635205, 2020). "For gastric acid, insulin (glucose), and thyroxin, Fhyper is smaller than Fhypo, consistent with autoimmune disease." (PMID 32433950, 2020). "Type 1 diabetes (T1D) is a common autoimmune disease that is characterized by insufficient insulin production." (PMID 33067559, 2020).